RET (ret proto-oncogene)
Diseases named in the same sentence as RET in open-access papers (continued):
Sharing a sentence is not in itself a finding about the gene and the disease.
papillary thyroid carcinoma (continued). "Analyses in larger cohorts are warranted to clarify the precise prevalence and characteristics of thyroid papillary carcinomas that present with NCOA4-RET (RET/PTC3)." (PMID 29088743, 2017). "The TPC-1 cell line was originally derived from a human papillary thyroid carcinoma containing rearrangements of the RET gene (RET/PTC)." (PMID 27816963, 2016). "Examples include the PAX8/PPARγ fusion gene described in follicular thyroid carcinomas and adenomas or RET/PTC fusion genes reported in papillary thyroid carcinomas and Hashimoto’s thyroiditis." (PMID 25898411, 2015). "The NCOA4α isoform observed in patient 2 was nearly full length in comparison to the truncated NCOA4β isoform fused to RET exon 12 in papillary thyroid carcinoma and NSCLC adenocarcinoma." (PMID 26078337, 2015). "CCDC6 was originally identified upon rearrangement with RET in human thyroid papillary carcinomas generating the RET/PTC1 oncogene." (PMID 25970781, 2015). "Spatial proximity between distant chromosomal loci has been associated with chromosomal rearrangements, as observed between RET and the H4 genes located 30 megabases (Mb) apart on chromosome 10, involved in RET gene fusions in papillary thyroid carcinoma." (PMID 26684754, 2015). "CCDC6 was identified upon rearrangement with RET in papillary thyroid carcinomas (PTC) generating the RET/PTC1 oncogene detectable in about 20% of PTCs." (PMID 25970781, 2015). "RET/PTC3 junction oncogene is typical of radiation-induced childhood papillary thyroid carcinoma (PTC) with a short latency period." (PMID 24759995, 2014). "The prevalence of RET/PTC rearrangements in ATC was much lower than in papillary thyroid cancer reported in most of the studies (4% vs. 36%)." (PMID 24267151, 2013). "For instance, increased miR-187 expression is reported in tumors with RET/PTC gene rearrangement, whereas that of miR-221 and miR-22 is observed in tumors positive for BRAF and RAS mutations as well as papillary carcinomas with unclear mutation." (PMID 23815851, 2013). "RET/PTC (Rearranged in Transformation/Papillary Thyroid Carcinoma) re-arrangement, BRAF (V-Raf murine sarcoma viral oncogene homolog B) and RAS (Rat Sarcoma viral oncogene homolog) point mutations are frequently observed in papillary thyroid cancer." (PMID 24367375, 2013). "The data presented here define that CCDC6, a partner of RET in papillary thyroid carcinoma and in lung adenocarcinoma, fine modulates the CREB1-dependent transcriptional activity through sumoylation both in vitro and in vivo." (PMID 23145146, 2012). "The first oncogenic role of RET was described in the most common endocrine cancer, papillary thyroid carcinoma (PTC), as the result of genomic rearrangements leading to its constitutive activation and to increased cell survival, proliferation and motility." (PMID 23056499, 2012). "Greater than 70% of papillary thyroid carcinomas harbor mutations in BRAF, RAS, or RET/PTC resulting in activation of the mitogen-activated protein kinase pathway and roughly 75% of follicular thyroid carcinomas have mutations in either RAS or PAX/PPARγ." (PMID 22630170, 2012). "Tumor cell proliferation has recently been reported in papillary thyroid carcinoma through a signaling pathway where RET, MAPK, and CaMKII contributes." (PMID 22355350, 2012). "CCDC6-RET fusions have been originally found in about 20% of human papillary thyroid carcinoma, generating the oncogene RET/PTC1." (PMID 23145146, 2012). "RET/PTC rearrangements are the most frequent molecular changes in papillary thyroid carcinoma (PTC)." (PMID 21219595, 2011). "Specifically, upregulation of miR-187, miR-146b, and miR-155 was found to be significantly more pronounced in papillary carcinomas carrying RET/PTC rearrangements, a genetic event characteristically found in radiation-induced thyroid tumors." (PMID 22654559, 2011).
papillary thyroid carcinoma (continued). "Chromosomal rearrangements involving RET receptor tyrosine kinase (TK) protooncogene (RET/PTC) are a specific feature of papillary thyroid carcinoma (PTC)." (PMID 21219595, 2011). "TPC-1 is a papillary thyroid carcinoma (PTC)-derived cell line that spontaneously expresses the oncogene RET/PTC1." (PMID 20955590, 2010). "(ii) It was recently reported that let-7 has an influence on the RET-pathway by effecting the cell growth and differentiation of papillary thyroid cancer." (PMID 20614023, 2010). "Papillary thyroid carcinomas (PTC) frequently harbor activating rearrangements of RET (8–33%) or NTRK1 (5–15%) genes, both coding for receptor tyrosine kinases that exert control over a wide range of transcription factors." (PMID 19087340, 2008). "Oncogenic fusion events involving RET occur in a large percentage of papillary thyroid carcinomas and multiple fusion partners have been identified." (PMID 19087340, 2008). "Rearrangements of the RET tyrosine kinase receptor gene (RET/PTCs) are found in 2.6–34% of human papillary thyroid carcinomas (PTC) and are even more prevalent in radiation-induced paediatric PTC." (PMID 18985036, 2008). "RET/PTC is very frequent in radiation-induced childhood papillary thyroid carcinomas developed post-Chernobyl in contaminated areas." (PMID 16641909, 2006). "Rearrangements of the RET proto-oncogene, which has been localised to chromosomal band 10q11.2, represent the most frequent changes in thyroid papillary carcinomas." (PMID 16641909, 2006). "Transgenic mice carrying TRK and RET/PTC3 oncogenes develop thyroid papillary carcinomas; thyroid anaplastic carcinomas were, conversely, obtained in the Tg-SV40 mice." (PMID 16106252, 2005). "The major oncogene known to be involved in the genesis of papillary carcinoma of the thyroid is RET, although more recently BRAF has also been identified in a significant proportion of adult cases." (PMID 15150580, 2004). "Activation of the RET tyrosine kinase domain occurs in a proportion of thyroid papillary carcinomas." (PMID 8761374, 1996). "None of 528 non-thyroid tumours showed rearrangement of the RET proto-oncogene, whereas three out of 30 thyroid papillary carcinomas were positive for RET activation." (PMID 8353035, 1993). "It is known that the rearrangement of RET occurs in about 10%-20% of human thyroid papillary carcinomas." (PMID 8353035, 1993). "Abnormal expression of the RET gene is also observed in 20-40% of papillary thyroid carcinomas." (PMID 40677447, 2025). "Pathogenic somatic variants are also associated with MTC, and RET rearrangements are observed in papillary thyroid cancer, non-small cell lung cancer and pan-cancer syndromes." (PMID 40138217, 2025). "Considering somatic variants, RET GoF pathogenic variants are found in approximately half of sporadic MTC cases, and activating RET chromosomal rearrangements or gene fusions constitute oncogenic drivers in multiple solid tumours, including 10–20% papillary thyroid cancers (PTCs) and 1–2% of NSCLC." (PMID 40138217, 2025). "Rearranged during transfection (RET), an oncogenic protein, is associated with various cancers, including non-small-cell lung cancer (NSCLC), papillary thyroid cancer (PTC), pancreatic cancer, medullary thyroid cancer (MTC), breast cancer, and colorectal cancer." (PMID 39086985, 2024). "For instance, papillary carcinoma often harbors BRAF and RET/PTC mutations, while follicular carcinoma may involve RAS mutations." (PMID 39063564, 2024). "Thus, this study aimed to determine the prevalence of CCDC6::RET and NCOA4::RET fusions in Thai papillary thyroid carcinoma patients." (PMID 37188126, 2023). "Among the several histologic subtypes, thyroid papillary carcinoma, colon adenocarcinoma, breast and pancreatic ductal carcinoma, and intra-hepatic cholangiocarcinoma are the most frequent cancers with relatively high prevalence of RET fusion positivity." (PMID 36690680, 2023).
papillary thyroid carcinoma (continued). "To determine whether the transcriptional repressive effect of adefovir dipivoxil in MTC TT cells is specific to the RET promoter region, we used the papillary thyroid carcinoma (PTC) TPC1 cell line." (PMID 37046823, 2023). "RET fusions occur in approximately 10% of papillary thyroid carcinomas." (PMID 36690680, 2023). "Papillary thyroid cancers (PTCs) are driven in about 50–60% of cases by the BRAFV600E mutation, while 5–20% of cases show fusion genes such as RET/PTC, PAX8-PPARG, and NTRK1/3 rearrangements, and 10–15% show RAS mutations (Cancer Genome Atlas Research 2014, Fagin & Wells 2016)." (PMID 36862025, 2023). "Papillary thyroid carcinoma could harbour BRAF mutations, RET/PTC rearrangements, and RAS mutations." (PMID 35328664, 2022). "However, few patients can benefit from these drugs because RET rearrangements have been described in approximately 10% to 20% of patients with papillary thyroid carcinoma and NTRK fusions in 5% to 25% of patients with DTC." (PMID 36202602, 2022). "Based on our experience treating RET-rearranged papillary thyroid cancer, we suspected that an incomplete clinical response to RET inhibition may be due to adaptive resistance leading to rebound ERK activation." (PMID 35510953, 2022). "We analyzed the TCGA papillary thyroid cancer dataset and found that RET-rearranged cancers have higher levels of ERK activity compared with BRAF/RAS mutant cancers, which may be the basis for a sensitivity to adaptive resistance after RET inhibition." (PMID 35510953, 2022). "Therefore, it would be very interesting to further investigate these functional aspects of OGG1 in papillary thyroid carcinoma with RET/TPC rearrangements." (PMID 35269445, 2022). "Papillary thyroid cancer is mainly reported to be associated with the missense mutation of B-raf proto-oncogene (BRAF, serine/threonine kinase) and rearrangement of RET/PTC1, RET/PTC3, and neurotrophic tyrosine kinase-1/3 (NTRK1/3) genes." (PMID 33805984, 2021). "Instead, RET fusions are frequently found in NSCLC as well as in papillary thyroid cancer and could result in either ligand-independent activation or aberrant RET expression." (PMID 34503226, 2021). "Interestingly, KRAS or BRAF mutations, as well as RET/PTC rearrangements, characterize the vast majority of papillary thyroid carcinoma (PTC)." (PMID 34065197, 2021). "Inhibition of α5β1 binding to ECM prevents attachment of FTC cell lines to the bone matrix, while RET-induced cell adhesion and migration of papillary thyroid carcinoma (PTC) cell lines required β1 and β3 integrins in vitro and in a mouse tumor xenograft model." (PMID 34208249, 2021). "For instance, the PKI sorafenib inhibits the kinases RAF, BRAF, FLT3, VEGFR 1–3, PDGFR, c-KIT and RET and significantly improves progression-free survival compared with placebo in patients with progressive radioactive iodine-refractory differentiated thyroid cancer." (PMID 34888523, 2021). "RET chromosomal rearrangements were initially identified in 5–40% of papillary thyroid cancers." (PMID 29455670, 2018). "TheRET fusion genes discovered in these studies include CCDC6-RET (already known as RET/PTC1 in papillary thyroid carcinoma) as well as a novel fusion with KIF5B (kinesin family member 5B), encoding a coiled coil domain, generated by pericentric inversion in chromosome 10." (PMID 27429741, 2016). "Some papillary thyroid carcinomas, including those arising after ionizing radiation exposure, develop through translocations resulting in fusion of RET with 1 of 13 other genes (RET/PTC rearrangements) producing a protein with constitutively active tyrosine kinase signaling." (PMID 26793165, 2015). "Our results strongly suggest that siRNA RET/PTC3-SQ NPs could be accredited as a potential new pharmacological approach for papillary thyroid carcinoma with RET/PTC3 junction oncogene." (PMID 24759995, 2014).
papillary thyroid carcinoma (continued). "Fragile sites FRA10C and FRA10G may be involved in the formation of the oncogenic RET/PTC rearrangement in papillary thyroid carcinoma." (PMID 25238782, 2014). "RET/PTC rearrangement was also found to account for 25–30% of papillary thyroid carcinoma cases." (PMID 23326756, 2012). "In clinical studies, 30-50% of papillary carcinomas are present RET/PTC in the cytological sample extracted by FNAB, but its analysis is difficult and may only be useful in combination with other markers." (PMID 22654559, 2011). "In papillary thyroid cancer, reduced expression of let-7f might be an essential molecular event in RET/PTC malignant transformation." (PMID 21533124, 2011). "This study, together with our previous study, would indicate that RET rearrangement is not the initiating event in papillary carcinomas associated with radiation exposure following the Chernobyl accident." (PMID 16641909, 2006). "RET is activated in papillary carcinoma by rearrangement of its tyrosine kinase domain." (PMID 15150580, 2004). "The two rearrangements resulting from inversion of part of chromosome 10 (PTC1 and PTC3) accounted for the majority of RET rearrangements identified, with PTC1 being associated with papillary carcinomas of the classic and diffuse sclerosing variants and PTC3 with the solid/follicular variant." (PMID 10646883, 2000). "Interestingly, in both cases of ATC developed by RET/PTC1TG;Patz1+/− mice, the anaplastic phenotype co-existed with a solid variant of PTC, suggesting that it has arisen from pre-existing aggressive papillary carcinomas." (PMID 29584698, 2018). "We found a significant association between the localization of RET mutations and the expression of three genes: NNAT (suggested to be a tumour suppressor gene), CDC14B (involved in cell cycle control) and NTRK3 (tyrosine receptor kinase that undergoes rearrangement in papillary thyroid cancer)." (PMID 28181547, 2017). "In approximately 20% of human papillary thyroid carcinoma (PTC), RET exons encoding the tyrosine kinase domain are fused to the promoter region and the 5’-ter exons of heterologous genes, generating chimeric oncogenes, such as CCDC6-RET (RET/PTC1) or NCOA4-RET (RET/PTC3)." (PMID 26046350, 2015). "Rearranged during transfection (RET) fusions drive subsets of non-small cell lung cancer (NSCLC) and papillary thyroid carcinoma (PTC)." (PMID 41194587, 2025). "The K1 and TPC-1 cell lines are derived from papillary thyroid carcinoma and carry, respectively, the following genetic aberrations: BRAFV600E and RET/PTC1 fusion." (PMID 39061242, 2024). "Selpercatinib and pralsetinib were approved in 2020 for patients with metastatic RET fusion-positive NSCLC, advanced or metastatic RET-altered MTC and papillary thyroid carcinoma." (PMID 37743366, 2023). "Lenvatinib primarily targets VEGFR and FGFR family members and, to a lesser extent, RET and KIT and is approved as monotherapy for the treatment of hepatocellular carcinoma and differentiated thyroid cancer." (PMID 36808802, 2023). "There are only few in vitro studies on this compound showing a high selectivity for RET (IC50 of 8 nM) and an ability to inhibit RET signaling in breast cancer (MCF-7) and papillary thyroid carcinoma (TPC-1) cell lines at low concentrations." (PMID 36139603, 2022). "In papillary thyroid cancers (PTCS), the new gene fusion involves exons 1–4 from the 5′ end of the TFG fused to the 3′ end of RET tyrosine kinase, leading to a TFG-RET fusion that transforms immortalized human thyroid cells in a kinase-dependent manner." (PMID 36337204, 2022). "RET gene rearrangement or fusion occurs in 1–2% of NSCLC and 10–20% of papillary thyroid carcinoma (PTC)." (PMID 36557971, 2022). "Vandetanib selectivity for RET was further validated in a D. melanogaster model of MEN2 syndromes and papillary thyroid carcinomas, suggesting that vandetanib can inhibit multiple RET isoforms to treat RET-dependent carcinomas." (PMID 35957881, 2022).
papillary thyroid carcinoma (continued). "Oncogenic RET fusions occur infrequently in diverse types of cancer, including NSCLC (1–2%), and more frequently in papillary thyroid cancers (10–20%)." (PMID 34832869, 2021). "RET fusions were potentially clinically actionable in two patients with CUP and papillary thyroid cancer." (PMID 34385467, 2021). "Two well-characterized papillary thyroid cancer cell lines, TPC-1 and BCPAP, harboring the RET/PTC and BRAFV600E oncogenes, respectively, were used to investigate the role of the integrin α3β1 in adhesion to ECM." (PMID 34208249, 2021). "For example, RET/PTC1 rearrangement, which is a key somatic genetic alteration in papillary thyroid cancer development, occurs more frequently in younger patients." (PMID 33082385, 2020). "RET fusions have been described in up to one-third of papillary thyroid cancers and in 2% of lung adenocarcinoma cases; CCDC6-RET and NCOA4-RET are the most commonly identified RET fusions." (PMID 32411236, 2020). "Preliminary results from 35 patients with RET-fusion positive tumors (27 NSCLC, 7 papillary thyroid cancer, 1 pancreatic cancer), treated with LOXO-292 showed a good tolerability, with none AEs graded ≥3, and an overall response rate (ORR) of 69%." (PMID 31731495, 2019). "The results of RET/PTC1 rearrangement in 10 FNA and paired FFPE papillary thyroid carcinoma (PTC) specimens showed complete correlation." (PMID 28417935, 2017). "In addition, the proto-oncogene RET/PTC induces nuclear accumulation of β-catenin in PTC by activating the PI3K/AKT and MAPK signaling pathways, but the precise mechanism underlying β-catenin dysregulation in differentiated thyroid carcinoma remains unknown." (PMID 29383135, 2017). "The specificity of berberine was demonstrated by using the papillary thyroid carcinoma TPC1 cell line, which lacks the G-quadruplex forming sequence on the RET promoter region due to chromosomal rearrangement." (PMID 26307103, 2015). "Fusions defining subtypes within a cancer include RET and NTRK gene fusions in subsets of papillary thyroid carcinoma, while PAX8-PPARγ fusions characterize subsets of follicular thyroid carcinoma." (PMID 26684754, 2015). "In the context of solid tumors, rearrangements of the RET (rearranged during transfection) gene, known as RET/PTC rearrangements occur in papillary thyroid carcinoma (PTC)." (PMID 24704845, 2012). "RET fusions (involving CCDC6, PRKAR1A, NCOA4 (ELE1), GOLGA5, TRIM24 (HTIF1), TRIM33 (RFG7), and KTN1 and ERC1 (ELKS)) are found in papillary thyroid cancers." (PMID 22928112, 2012). "Chromosomal rearrangements involving the RET gene, known as RET/PTC, are prevalent in thyroid papillary carcinomas from patients with radiation exposure history." (PMID 22655027, 2012). "To further understand the role of CCDC6 in PP4c activity modulation we utilized a human CCDC6-null cell line, the thyroid papillary carcinoma TPC-1 cell line, that carries the RET/PTC1 oncogene and has lost by deletion the normal unrearranged CCDC6 allele." (PMID 22655027, 2012). "RET/PTC3 is a fusion oncoprotein expressed in the thyroid epithelium of patients afflicted with thyroid autoimmune disease and/or differentiated thyroid carcinoma." (PMID 18304343, 2008). "Furthermore, since Lc2/AD represents the only available model harboring RET rearrangement for NSCLC, we employed TPC1 cells, a papillary thyroid cancer (PTC) cell line carrying CCDC6-RET fusion." (PMID 40405293, 2025). "The most common fusions of the RET gene are NCOA4-RET and CDCC6-RET in papillary thyroid carcinoma." (PMID 36646686, 2023). "Papillary thyroid carcinoma and non-small cell lung cancer are not the only neoplasms that present RET rearrangements." (PMID 36358717, 2022).